IL5 (interleukin 5)
Diseases named in the same sentence as IL5 in open-access papers (continued):
Sharing a sentence is not in itself a finding about the gene and the disease.
focal epilepsy (1 paper, 2024). A seizure caused by a localized disorder. "Our study has shown a positive association between IL-5 and the development of focal epilepsy." (PMID 39259090, 2024). "The findings suggested that increased levels of interleukin-1 receptor antagonists and interleukin-5 may be significantly associated with increased risks of focal epilepsy (beta: 0.080, P = .043; beta: 0.083, P = .015)." (PMID 39259090, 2024). "Kyoto Encyclopedia of Genes and Genomes and gene ontology analyses consistently indicated that IL5 is primarily involved in metabolic processes, behavioral regulation, and synthesis of synaptic membrane components in focal epilepsy." (PMID 39259090, 2024). "Specifically, focal epilepsy onset may induce increases in cytokines such as IL-7, IL-1Ra, IL-10, TNF-α, IFN-γ, and IL-1β, whereas inconsistent cytokine levels, including IL-5 and IL-1ra, may influence variations in focal epilepsy risk." (PMID 39259090, 2024). "IVWs indicate that genetically increased IL-5 levels may increase the likelihood of developing focal epilepsy (OR: 1.084, 95% CI: 1.015–1.157, P = .015)." (PMID 39259090, 2024).
G6PD deficiency (1 paper, 2023). An X-linked genetic condition caused by alterations in the gene G6PD that result in moderately to severely decreased activity levels of the enzyme glucose-6-phosphate dehydrogenase. "G6PD deficiency has been associated with a proinflammatory state with over-expression of IL-8, IL-4, IL-5, and IL-9 cytokines, and increased chemotaxis of eosinophils and Th2 immune polarization." (PMID 37753082, 2023).
Glucose intolerance (1 paper, 2017). Glucose intolerance (GI) can be defined as dysglycemia that comprises both prediabetes and diabetes. "Following a high fat diet, Il5 deficient mice display increased weight gain, adipose tissue weight, fasting glucose levels and exhibit glucose intolerance as well as insulin resistance." (PMID 28725048, 2017). "Finally, g) Cd300f−/− mice displayed a dramatic reduction in diet-induced weight gain and glucose intolerance in the presence of elevated IL-5 levels." (PMID 28725048, 2017).
gout (1 paper, 2019). A condition characterized by painful swelling of the joints, which is caused by deposition of urate crystals. "IL-5, IL-10, and IL-12 levels gradually decreased from control, subsequently hypouricemia, and gout to gout attack group." (PMID 31739430, 2019). "On the other hand, IL-5, IL-10, and eotaxin were lower in patients with acute gout inflammation, which can be explained by their role in inhibiting inflammation (IL-10) or eosinophilic inflammation (IL-5, eotaxin)." (PMID 31739430, 2019).
H1N1 influenza (1 paper, 2015). "Despite the increase observed in both obese patient groups, it is important to note that compared with ILI patients and AHCs, non-obese patients with severe clinical pictures of H1N1 influenza have increased IL-5 levels." (PMID 26657940, 2015).
hair disorders (1 paper, 2022). "Notably, no pharmacovigilance signal for hair disorders associated with anti-IL-5 biologics (mepolizumab, reslizumab, and benralizumab) was found, even though those have been reported in VigiBase." (PMID 35895603, 2022).
hantavirus infection (1 paper, 2011). "To further analyze the relation of pro- and anti-inflammatory cytokines during the course of disease in acute hantavirus infection, we compared expression of IL-2, IL-5, IL-6." (PMID 22085404, 2011). "Cytokine expression of IL-2, IL-5, IL-6, IL-8, IL-10, IFN-γ, TNF-α and TGF-β1 was analysed by ELISA during the early and late phase of acute hantavirus infection (average 6 and 12 days after onset of symptoms, respectively)." (PMID 22085404, 2011).
hearing loss (1 paper, 2024). "These cytokines, which act through different pathways (IL-2 in TH1 and IL-5 in TH-2), are associated with hearing loss in a few articles." (PMID 39015324, 2024).
Hematuria (1 paper, 2024). The presence of blood in the urine. "On further analysis, the authors also reported that elevated levels of schistosome-specific IL-10 preceded Sh reinfection, and high levels of IL-5 were associated with hematuria." (PMID 39250522, 2024).
Hepatosplenomegaly (1 paper, 2009). Simultaneous enlargement of the liver and spleen. "The circulating levels of IL-6 and IL-5 were found to have statistically significant relationships with hepatosplenomegaly, but in a non-linear fashion." (PMID 19149774, 2009).
heroin addicts (1 paper, 2021). "The analysis revealed that the levels of IL-1ra, IL-1β, IL-5, IL-12p70, IL-13, IL-15, MIP-1β, bFGF, and RANTES in the plasma of heroin addicts in the AW and PW stages were not significantly different from those in the plasma of the control group subjects (data not shown)." (PMID 34489980, 2021).
herpes labialis (1 paper, 2019). A lesion caused by type 1 or type 2 herpes simplex virus, typically involving the oralfacial region. "Higher IFNG and lower IL5 expression by PBMCs in the presence of HSV‐1 correlate with fewer herpes labialis outbreaks, and a single topical dose of SADBE to the arm of subjects with frequent herpes labialis episodes improves immune response to HSV‐1." (PMID 30756512, 2019).
herpetic keratitis (1 paper, 2023). "Importantly, a previous study found that DMF improved herpetic keratitis by increasing IL-4 and IL-5 secretion, both Th2-related cytokines, by activated lymphocytes." (PMID 37371900, 2023).
histoplasmosis (1 paper, 2021). A disease caused by the fungus Histoplasma capsulatum. "Here, we also described increased levels of IL-5 in BAL samples from the non-HIV histoplasmosis group, although significance was not reached." (PMID 34829225, 2021).
hyperferritinemia (1 paper, 2020). "Indeed, in addition to significantly reducing the serum levels of IL-6 and C-reactive protein (CRP), ruxolitinib could influence the regulation of several inflammatory cytokines (including IL-2, IL-5, and IL-10), and consequently reduce hyperferritinemia." (PMID 33489899, 2020).
Hyperinsulinemia (1 paper, 2021). An increased concentration of insulin in the blood. "Metformin and hyperinsulinemia changed the expression of extracellular proteins (e.g. metformin: CTSL, EGFR, IL5, KLK3; insulin: IL4, IL15, PGC, SORL1)." (PMID 33690729, 2021). "A significant protein upregulation compared to the untreated control was induced by metformin, but not by hyperinsulinemia, for immune regulatory factors such as IL5 and peptidase inhibitor 3 (PI3, elafin (ELAF))." (PMID 33690729, 2021).
hyperlipidemia (1 paper, 2024). "In hyperlipidemia, IL‐1β, IL‐6, IL‐8, and IL‐10 still had significant differences between the SAP group and non‐SAP group (p < .05), while IL‐5, IL‐17, TNF‐α had no statistical differences between the two groups." (PMID 38411379, 2024).
hyperplasia (1 paper, 2022). An abnormal increase in the number of cells in an organ or a tissue with consequent enlargement. "Hyperplasia also occurs on the stimulation of T-lymphocytes that produce several cytokines, such as IFN-γ, IL-2, IL-5, and IL-10, subsequently leading to cell proliferation." (PMID 36614420, 2022).
hyperthyroidism (1 paper, 2025). Overactivity of the thyroid gland resulting in overproduction of thyroid hormone and increased metabolic rate. "Once infected with H. pylori, cytokines such as interleukin (IL)-4, IL-5, and IL-6 are activated, initiating a cascade of humoral immune responses that may modify the expression of adhesion molecules on the gastric mucosa, thereby contributing to the hyperthyroidism observed in GD." (PMID 39963276, 2025).
Intellectual disability (1 paper, 2011). "Elevated concentrations of IFN-γ, IL-4 and IL-5 in midgestation maternal serum were significantly associated with a 50% increased risk of ASD, regardless of ASD onset type and the presence of intellectual disability." (PMID 21810230, 2011).
interstitial lung disease (1 paper, 2025). A diverse group of lung diseases that affect the lung parenchyma. "Remarkably, the interstitial lung disease showed near‐complete reversibility following targeted inhibition of the IL‐5 pathway with mepolizumab, highlighting the potential role of Th2‐driven eosinophilic inflammation in the pathogenesis of certain forms of interstitial lung disease." (PMID 40641495, 2025). "The complete clinical remission and sustained radiological improvement observed with mepolizumab suggest that IL‐5 blockade may have interrupted a Th2‐driven profibrotic pathway in this form of interstitial lung disease." (PMID 40641495, 2025).
intestinal infection (1 paper, 2020). "H. polygyrus intestinal infection induces a IL-33–mediated activation of IL-5 secreting Th2 cells and causes upregulation of IL-5–mediated eosinophils, leading to a significant increase in immune-mediated killing of N. brasiliensis larvae in the lungs of the co-infected mice." (PMID 33193446, 2020).
intestinal schistosomiasis (1 paper, 2016). An intestinal infection that is caused by Schistosoma japonicum. "Of interest, a recent comparisons of urogenital and intestinal schistosomiasis concluded that IL-5 responses to S. haematobium infections were stronger than those elicited by S. mansoni." (PMID 27152725, 2016).
iron deficiency anaemia (1 paper, 2010). "While levels of TNF, IFN-γ and IL-1β (type I) and IL-10 and IL-13 (type II) seemed decreased in iron deficiency anaemia, the levels of IL-12 and IL-5 appeared increased." (PMID 20546583, 2010). "Iron deficiency anaemia was associated with increased concentrations of IL-12 by 37%, and seemed associated with a 34% decrease in IL-5 concentrations." (PMID 20546583, 2010). "This seems supported by weak evidence of similar interaction in the same direction when examining the influence of iron deficiency anaemia on the association between IFN-γ and IL-5, and between IFN-γ and IL-13." (PMID 20546583, 2010).
keloid (1 paper, 2024). An irregularly shaped, elevated mark on the skin caused by deposits of excessive amounts of collagen during wound healing. "Some of them, such as IL-1β or IL-5, are not detected in keloid patients, and others are present in range between 20 and 40% patients." (PMID 39081787, 2024).
keratitis (1 paper, 2022). A corneal disease that is characterized by inflammation of the cornea. "However, IL-5 KO mice develop keratitis in the absence of eosinophils." (PMID 36389745, 2022).
keratoconjunctivitis (1 paper, 2017). Inflammation of both the cornea and the conjunctiva. "However, ILC2, like T cells (Th2 cells), may play a role in keratoconjunctivitis in IL33tg mice, as ILC2 can produce massive IL-5 and IL-13 in response to the stimulation of IL-334, and those Th2 cytokines are produced by ILC2 in the corneas of IL33tg mice." (PMID 28855579, 2017).
leiomyoma (1 paper, 2021). A well-circumscribed benign smooth muscle neoplasm characterized by the presence of spindle cells with cigar-shaped nuclei, interlacing fascicles, and a whorled pattern. "Numerous studies described leiomyoma cells exhibiting a significantly greater expression of IL1, IL4, IL5, IL6, IL10, IL11, IL13, and IL15." (PMID 34442017, 2021).
leishmaniasis (1 paper, 2015). Infectious disease that is transmitted through the bite of hematophagous female phlebotomine sand flies. "The production of IFN-γ, TNF-α, granzyme B, IL-5 and IL-10 by SLA-stimulated PBMCs, and of IFN-γ, TNF-α and IL-2 by SLA-stimulated whole blood, could be used to indicate exposure to leishmaniasis, especially for patients subjected to induced immunosuppression." (PMID 26496365, 2015).
liver cirrhosis (1 paper, 2023). "Our preliminary data, although obtained from a limited number of patients, identified cytokine associations, and specifically IL-5 and IL-15, potentially predictive of HCC onset in patients with decompensated liver cirrhosis." (PMID 37686245, 2023).
lymphopenia (1 paper, 2016). Reduction in the number of lymphocytes. "The high production of the cytokines IL-10 and IL-5 with CD4 lymphopenia is likely to be a cause of the aggressive disease and the pulmonary spread." (PMID 27711109, 2016).
macular edema (1 paper, 2017). "This study showed as a result of the examination 2 that eotaxin-1, IP-10, MIP-α, IL-5, IL-8, IP-10, and MIP-1β was relevant to the effectiveness of IVR in reducing macular edema." (PMID 28346545, 2017).
magnesium deficiency (1 paper, 2010). A nutritional condition produced by a deficiency of magnesium in the diet, characterized by anorexia, nausea, vomiting, lethargy, and weakness. "Magnesium deficiency was associated with an 80% increase in IL-13 concentrations, and seemed associated with a 49% increase in IL-5 concentrations." (PMID 20546583, 2010).
meningioma (1 paper, 2012). A generally slow growing tumor attached to the dura mater. "The IFN-γ/IL-5 ratios in both primary GBM patients (geometric mean 3.7) and recurrent GBMs (geometric mean 0.9) were significantly lower than those in healthy subjects (geometric mean 16.0) and meningioma patients (geometric mean 10.0) (p<0.001)." (PMID 23186108, 2012).
mesothelioma (1 paper, 2024). A usually malignant and aggressive neoplasm of the mesothelium which is often associated with exposure to asbestos. "Importantly, our data shows that 2 central cytokines modulating eosinophil fate (i.e., IL-5 and IL-33) do not significantly modify tumour growth kinetics in a mouse model of mesothelioma." (PMID 39471751, 2024).
microhematuria (1 paper, 2021). "IL-5 induces eosinophil maturation and an IL-5 response to Schistosoma antigens has been associated with microhematuria in children with S. haematobium infection." (PMID 33737927, 2021).
mononucleosis (1 paper, 2022). "This indicates that patients with stomach pain, bloating, and symptoms of an irritable bowel at baseline, severe gastrointestinal symptoms when they contracted mononucleosis, and low levels of IL-13 and/or IL-5 at baseline had nearly an 80% chance of developing severe ME/CFS six months following IM." (PMID 35350440, 2022).
myasthenia gravis (1 paper, 2020). Myasthenia gravis (MG) is a rare, clinically heterogeneous, autoimmune disorder of the neuromuscular junction characterized by fatigable weakness of voluntary muscles. "Eight associations (five variants) were not previously reported to our knowledge, including associations near IRF1/IL5 for myasthenia gravis, near TNFSF11 for RF− JIA, and near CD2/CD28 for EGPA." (PMID 33239102, 2020).
myelodysplastic syndrome (1 paper, 2012). A clonal hematopoietic disorder characterized by dysplasia and ineffective hematopoiesis in one or more of the hematopoietic cell lines. "Hence, in absence of Th-2 cytokines (IL-4 and IL-5), cytokine imbalances associated with exaggerated Th-1 cytokines may occur in a subset of 5q minus myelodysplastic syndrome." (PMID 22934211, 2012). "Due to the absence of Th-2 cytokines, such as IL-4 and IL-5, in a subset of 5q minus myelodysplastic syndrome, proinflammatory Th-1 cytokines such as IFN-γ and TNF-α may be exaggerated in an environment conducive to antigen expression." (PMID 22934211, 2012).
myopia (1 paper, 2025). "The aqueous humor from mCNV patients contained elevated levels of IL-8 and C−X−C motif chemokine ligand 10 (CXCL10), platelet−derived growth factor (PDGF), IL-2, IL-5, IL-13, IL-15, IL-17A and TNF-α compared to the aqueous humor from simple myopia." (PMID 40909333, 2025). "IL-5 and CXCL10 were significantly higher in high myopia and rhegmatogenous retinal detachment." (PMID 40909333, 2025).
neurofibroma (1 paper, 2025). An intraneural or extraneural neoplasm arising from nerve tissues and neural sheaths. "Notably, MEK inhibition reduced expression of IL5 in neurofibroma lysates, correlating with reduced tumor growth." (PMID 40075752, 2025). "IL5 is largely known for its effects on eosinophils and B cells; neither of these cell types has been described in neurofibromas." (PMID 40075752, 2025).
neurosarcoidosis (1 paper, 2025). A sarcoidosis that involves the nervous system. "Compared to neurosarcoidosis patients, the CSF of GFAP‐IgG‐positive patients had higher concentrations of IL5 (P = 0.001) and lower concentrations of GM‐CSF and IFN‐gamma (P < 0.01 for each)." (PMID 39869499, 2025).
obstructive uropathy (1 paper, 2022). "The study showed increased levels of IL-5, γ-interferon, and eotaxin in the kidneys with an obstructed system, among which IL-5 and γ-interferon were highly (p < 0.05) associated with the severity of obstructive uropathy." (PMID 35558565, 2022).
osteomyelitis (1 paper, 2023). An acute or chronic inflammation of the bone and its structures due to infection with pyogenic bacteria. "On the other hand, P2 emphasizes the role of early initiation of therapy with an IL-5-/IL-5R-targeting mAb to avoid CS toxicity, as the CS effect on bone reabsorption is a secondary insult to a patient presenting with a pathologic bone fracture from osteomyelitis." (PMID 37187735, 2023).
otitis media with effusion (1 paper, 2025). Otitis media associated with accumulation of fluid in the middle ear. "The analysis of cytokine levels in adults with OME, including IL-2, IL-4, IL-5, IL-10, IL-12, and interferon (IFN)-gamma, reveals distinct patterns associated with otitis media with effusion (OME) and allergic conditions." (PMID 40497981, 2025).
Paralysis (1 paper, 2017). Paralysis of voluntary muscles means loss of contraction due to interruption of one or more motor pathways from the brain to the muscle fibers. "Animals treated with both rIL-5 and anti-IL-5 mAb from day 8 post-immunization had lower clinical paralysis scores than controls at days 10, 11, and 12 and later recovered." (PMID 29163523, 2017).
pemphigoid (1 paper, 2022). "The presence of eosinophils in the areas affected by the inflammatory lesions of pemphigoid is favored by chemokines such as eotaxin, with higher-than-normal concentrations in both serum and blister fluids of IL-5." (PMID 36359364, 2022).
Pf (1 paper, 2019). "Pairwise mean differences of the cytokine levels between all the infected groups showed that individuals infected with only Na had significantly higher CCL11 and IL-5 levels compared to those with either Pf only or concurrent Na/Pf infections." (PMID 33604551, 2019).
pneumococcal infection (1 paper, 2022). Infections with bacteria of the species streptococcus pneumoniae. "As expected, the classic type-2 cytokines IL4, IL5, and IL-13 were increased in the lungs of HDM-exposed mice, and pneumococcal infection did not alter their respective levels." (PMID 35273509, 2022).
proliferative diabetic retinopathy (1 paper, 2025). Advanced retinopathy due to diabetes mellitus characterized by the formation of new vessels in the retina. "Patients with non-proliferative diabetic retinopathy and proliferative diabetic retinopathy exhibit elevated IL-5 levels compared to diabetic patients without retinopathy." (PMID 39347908, 2025). "Additionally, the concentration of IL-5 is higher in the proliferative diabetic retinopathy group than in the non-proliferative diabetic retinopathy group." (PMID 39347908, 2025).
prostatitis (1 paper, 2025). An infectious or non-infectious inflammatory process affecting the prostate gland. "Reverse MR analysis suggests that prostatitis can reduce the levels of 3 inflammatory cytokines: chemokine (C-C motif) ligand 23 (CCL23), IL-5, and TNF-related activation-induced cytokine (TRANCE)." (PMID 40355178, 2025).
pseudoexfoliation glaucoma (1 paper, 2025). "Earlier, we showed that elevated IOPs were significantly correlated with the intracameral levels of IL-5, IL-6, IL-8, IL-10, IL-15, IL-17, and CCL2 in eyes with pseudoexfoliation glaucoma." (PMID 40353220, 2025).